HMGA1 (high mobility group AT-hook 1)
Diseases named in the same sentence as HMGA1 in open-access papers (continued):
Sharing a sentence is not in itself a finding about the gene and the disease.
breast carcinoma (continued). "In addition, higher HMGA1 expression levels were also observed in the ductal breast cancer cases compared with the lobular breast cancer cases (P=0.000)." (PMID 25572132, 2015). "Additionally, the miRNA miR-181b has been shown to be up-regulated by HMGA1 and both are supposed to be involved in breast cancer progression." (PMID 26627005, 2015). "Interestingly, in breast carcinoma, HMGA1 takes part in an important regulatory circuitry involving CBX7 and miR-181b microRNA (miRNA)." (PMID 25859543, 2015). "In addition, the higher HMGA1 expression gene signature was associated with both the basal-like subtypes and high-grade (G3) breast cancers and was also correlated with HMGA1 mRNA expression." (PMID 23945276, 2013). "We clearly demonstrated that breast cancer cell lines in which HMGA1 has been depleted behave as an organised epithelial sheet and that their migration and invasion ability are dramatically decreased both in vitro and in vivo, even if tumour growth is not impaired." (PMID 23945276, 2013). "In line with our results relative to HMGA1 expression in primary tumour specimens from breast cancer patients, we demonstrated that the HMGA1 gene signature is correlated with the more aggressive and undifferentiated basal-like subtype, with high relapse rates and poor patient survival." (PMID 23945276, 2013). "Moreover, we demonstrated that breast cancer cells in which HMGA1 has been depleted lack self-renewal capability and lose the ability to form mammospheres in culture." (PMID 23945276, 2013). "Moreover, expression of HMGA1 and 8 additional genes predicted poor outcomes in breast cancer, as well as brain and bladder cancer." (PMID 23658826, 2013). "Thus, our pathway analysis further confirms the important role for HMGA1 in regulating embryonic stem cell networks during tumor progression in breast cancer." (PMID 23658826, 2013). "Notably, HMGA1 depletion in basal-like breast cancer cell lines reduced migration and invasion in vitro and the formation of metastases in vivo." (PMID 23945276, 2013). "This study aimed to deepen our understanding of the role of HMGA1 in breast cancer metastasis." (PMID 23945276, 2013). "This hypothesis is supported by the evidence that adenovirus carrying the HMGA1 gene in an antisense orientation induces programmed cell death in carcinoma cell lines derived from human thyroid, lung, colon, and breast cancers." (PMID 14647145, 2003). "HMGA1 has been reported to contribute to estrogen-independence, tumor progression, and poor outcomes and could serve as a prognostic marker and therapeutic target for breast cancer." (PMID 38706894, 2024). "For instance, HMGA1 may promote breast cancer aggressiveness and angiogenesis." (PMID 37710236, 2023). "HMGA1P6 and HMGA1P7, two pseudogenes of HMGA1 competing for endogenous RNA, can also lead to cancer when they are dysregulated, and the expression of HMGA1P7 is related to the levels of H19 and IGF2 in breast cancer, which is linked to the high double strand breaks in breast cancer cells." (PMID 35864955, 2022). "Moreover, HMGA1 is known to support the growth and progression of breast cancers." (PMID 35610507, 2022). "However, the contribution of HMGA1 in breast cancer remains to be tapped." (PMID 36479041, 2022). "By gene silencing experiments, we found that HMGA1 downregulation could inhibit cell proliferation through inducing G1 phase arrest and S phase inhibition, induce cell apoptosis, and weaken the migrating and invasive ability of breast cancer cells." (PMID 36479041, 2022).
breast carcinoma (continued). "Studies have found that the HMGA1 gene does not rearrange and mutate in breast cancer." (PMID 35864955, 2022). "Notably, overexpression of HMGA1 has been detected in breast cancer and neuroblastoma." (PMID 35629376, 2022). "However, the detailed mechanism of HMGA1 in breast cancer still needs further exploration." (PMID 36479041, 2022). "Additionally, HMGA1 regulates angiogenesis in breast cancer and chemoresistance in gastric cancer." (PMID 35130798, 2022). "Immunohistochemistry and statistical analysis of HMGA1 in breast cancer showed that its expression is correlated with the histological grade, clinical stage, tumour size, lymph node metastasis, distant metastasis and whether it correlates with triple‐negative breast cancer." (PMID 30614613, 2019). "These authors observed that silencing HMGA1 could block oncogenic properties, including proliferation, migration, invasion, and tumorigenesis, in triple-negative (resistant) breast cancer cells by reprogramming cancer cells through stem cell transcriptional networks." (PMID 28290473, 2017). "However, the correlation between TGF-β1 and HMGA1 in breast cancer cell is not yet well understood." (PMID 25572132, 2015). "We also found that silencing HMGA1 depletes tumor initiator/cancer stem cells, indicating that targeting HMGA1 in breast cancer therapy could have an important impact on the cancer stem cell population, which is believed to be the basis for refractory disease in diverse tumors." (PMID 23658826, 2013). "Hence, the genes up-regulated by the HMGA1 protein have prognostic significance, and their combined expression may be considered as a marker of breast cancer malignancy." (PMID 23945276, 2013). "Drug sensitivity analysis further revealed that HMGA1 predicted resistance to AKT inhibitors, which was experimentally validated in breast cancer cells treated with Capivasertib." (PMID 41463532, 2025). "Collectively, these findings underscore HMGA1 as a key marker and potential mediator of resistance to AKT inhibition in aggressive breast cancer subtypes." (PMID 41463532, 2025). "High Mobility Group AT-Hook 1(HMGA1), an oncofetal protein, plays a role in the progression of breast cancer." (PMID 39040191, 2024). "The results showed that endothelial cells in tumors are specifically dominated by HMGA1 and HEYL, both of which have been found as promoters of neoangiogenesis in breast cancers." (PMID 38414027, 2024). "Through referring to others’ YB1-CLIP results (GSE63605), some onco-promoting gene mRNAs were found in the YB1-bound RNA library and the expression levels of HMGA1 and CD151 were investigated in breast cancer cells." (PMID 37035211, 2023). "The high mobility group A1 (HMGA1), a chromatin regulator, had been shown to suppress BRCA1 gene expression in human breast cancer." (PMID 36338996, 2022). "The expression of HMGA1 was analyzed in The Cancer Genome Atlas (TCGA) and TIMER database, and immunohistochemistry was performed in 39 breast cancer (BC) patients." (PMID 36479041, 2022). "HMGA1 can also negatively regulate CBX7, and CBX7 negatively regulates the expression of miR-181b to affect the progression of breast cancer." (PMID 35864955, 2022). "Inhibition of HMGA1 can regulate EMT and affect the metastasis and prognosis of cancer cells, which has been reported in non-small cell lung cancer, cervical cancer, breast cancer, thyroid cancer, and gastric cancer." (PMID 35629376, 2022). "To investigate the biological function of HMGA1 in breast cancer, we transfected MCF-7 and MDA-MB-231 cells with siRNA selectively targeting HMGA1." (PMID 36479041, 2022). "In previous study, a total of 21 proteomic signatures regulated by HMGA1 in breast cancer were reported, and three of them (KIFC1, LRRC59, and TRIP13) were verified to promote breast cancer progression." (PMID 33648560, 2021).
breast carcinoma (continued). "For example, miR-625 suppresses cell proliferation and migration of breast cancer cells by targeting the 3′-UTR of HMGA1 mRNA; consistent with this, overexpression of HMGA1 recovers the miR-625-mediated inhibition of cell proliferation." (PMID 31963852, 2020). "We performed also the reverse experiment by using a previously established cell line where HMGA1 is overexpressed in the Luminal A breast cancer cell line MCF7, where endogenous HMGA1 is barely detectable and cells exhibit an epithelial phenotype." (PMID 31167352, 2019). "From this catalogue, we selected a dataset of 818 breast cancer patients, and we found that FOXM1 was enriched in HMGA1 overexpressing patients, both at mRNA and protein levels." (PMID 31311575, 2019). "We observed that the silencing of HMGA1 and FOXM1 reduced the ability of breast cancer cells-conditioned medium to promote the proliferation of ECs." (PMID 31311575, 2019). "Firstly, we investigated the relationship between the combined expression of HMGA1 and FOXM1 with the VEGFA expression in breast cancer patients." (PMID 31311575, 2019). "To test in vivo the effect of HMGA1 on the DSB repair, we used the low HMGA1-expressing breast cancer MCF7 cells stably transfected with a plasmid expressing a HA-tagged HMGA1a (MCF7_HMGA1a) and control cells transfected with the empty vector (MCF7_CTRL)." (PMID 27723831, 2016). "Next, we investigated the possible relationship between HMGA1 and CCNE2 expression in breast cancer patients." (PMID 26265440, 2015). "Intriguingly, we found a clinically relevant relationship between HMGA1 and CCNE2 expression and the YAP/TAZ signature in breast cancer patients." (PMID 26265440, 2015). "Through Smads signaling, TGF-β1 is a well known inducer of EMT leading to tumor metastasis progression, and our data suggest that TGF-β1 promotes EMT by increasing the expression of HMGA1, offering a novel pathway for TGF-β1-induced EMT in breast cancer." (PMID 25572132, 2015). "Using basal-like breast cancer cell lines, we demonstrated that CCNE2 is an important downstream factor of HMGA1 that mediates tumor aggressiveness." (PMID 26265440, 2015). "In this study, we investigated the contribution of HMGA1 and CCNE2 to breast cancer cell migration and invasion." (PMID 26265440, 2015). "Similar to HMGA1, an upregulation of HMGA2 was reported in human lung and breast cancers as well as in a subset of canine PCs." (PMID 25276782, 2014). "Moreover, the presence of the HMGA1 protein has been correlated with a higher cancer grade in mammary epithelial cancer, suggesting that HMGA1 may be a key player in sustaining breast cancer." (PMID 23945276, 2013). "Given our observations that HMGA1 increases migration and invasion and supports EMT and breast cancer stemness, we assessed the functional roles of the HMGA1 gene signature." (PMID 23945276, 2013). "This provides a strong rationale to investigate whether HMGA1 modulates sensitivity to Capivasertib (AZD5363), a clinically relevant AKT inhibitor recently approved for breast cancer therapy." (PMID 41463532, 2025). "A putative cis-acting HMGA1 natural antisense transcript (NAT) was experimentally established and found to be expressed both in normal healthy pancreatic and breast epithelial cells and in pancreatic and breast cancer cells." (PMID 41183073, 2025). "LPA's connection to Imiquimod, as well as to Megestrol Acetate—a drug commonly used against breast cancer—may be analogous to the relationships observed with ZNF124 and HMGA1." (PMID 39744172, 2025). "Compared with the control group, OXPHOS-associated factors (NDUFA9 and SDHB) showed an obvious expression increase in YB1-silenced tumors, but the expression of HMGA1 was decreased significantly, suggesting the existence of an RNA displacement model in YB1-mediated breast cancer progression." (PMID 37035211, 2023).
breast carcinoma (continued). "miR-142-3p, which suppresses expression of the oncogene HMGA1 and targets the AKT/ERK/STAT3 pathway, is supposed to be a new miRNA for breast cancer therapy that restores this suppressive miRNA in tumor breast cells using a targeted nanoparticle delivery system." (PMID 36555323, 2022). "Next, we examined the expression of HMGA1 mRNA and protein in six breast cancer tissues and paired adjacent nontumor tissues and got consistent finding in TCGA database." (PMID 36479041, 2022). "The heatmap showed that the HMGA1-high cluster expressed TMSB10, CTSD and LGALS1, which are correlated with poor prognosis in breast cancer." (PMID 35611554, 2022). "Breast cancer cells overexpressing HMGA1 show a faster recovery upon induction of DNA DSBs via nonhomologous end-joining DNA repair." (PMID 34716319, 2021). "Overall, clinical datasets analysis confirmed that VEGFA expression positively correlates with HMGA1 and FOXM1, and that their presence has an impact on breast cancer development, since a signature combining HMGA1, FOXM1 and VEGFA expression is associated to a worse prognosis." (PMID 31311575, 2019). "We decided to study a nuclear protein called the high mobility group A1 (HMGA1) out of the group of non-classical secreted proteins since it was significantly over-secreted from invasive breast cancer cells." (PMID 31779212, 2019). "Furthermore, we demonstrate that HMGA1 and FOXM1 synergistically drive breast cancer cells to promote tumor angiogenesis both in vitro in endothelial cells and in vivo in a zebrafish xenograft model." (PMID 31311575, 2019). "Interestingly, the low survival probability of patients that co-express HMGA1, FOXM1 and VEGFA at high levels has also been observed both in breast cancer datasets and in a subset of TNBC patients." (PMID 31311575, 2019). "Moreover, in a TCGA dataset of breast cancer patients, we found an enrichment of VEGFA mRNA in HMGA1 or FOXM1 overexpressing patients." (PMID 31311575, 2019). "HMGA1 protein has this unique property because it is a master regulator in breast cancer cells that control the transition from a nontumorigenic epithelial-like phenotype toward a highly aggressive mesenchymal-like one." (PMID 26527623, 2016). "In addition, to have more robust data, we used also a highly expressing HMGA1 breast cancer cell line, MDA-MB-231, that has been silenced for HMGA1 expression through shRNA (MDA-MB-231_shA1_3)." (PMID 27723831, 2016). "Most human breast cancer cell lines exhibit higher HMGA1 expression levels with respect to nontransformed cell lines." (PMID 26527623, 2016). "Importantly, we show that HMGA1a enhances the activity of Ligase IV and that high levels of expression of HMGA1 protects breast cancer cells from a DSB genotoxic insult favouring the clearance of DSBs and cell survival." (PMID 27723831, 2016). "Next, we used basal-like breast cancer cell lines (MDA-MB-231 and MDA-MB-157) to assess whether CCNE2 expression is dependent on HMGA1 expression." (PMID 26265440, 2015). "In this study, to investigate the effects of TGF-β1 on the expression of HMGA1, the 2 breast cancer cell lines, MCF-7 and MDA-MB-231, with or without ER expression, respectively were utilized." (PMID 25572132, 2015). "Second, the functional validation performed in breast cancer models provides proof-of-concept but may not fully reflect HMGA1 activity across diverse cancer types." (PMID 41463532, 2025). "Moreover, the level of HMGA1 was prominently increased in breast cancer tissues compared with the adjacent nontumor tissues." (PMID 36479041, 2022). "In addition, HMGA1 upregulates the expression of cyclin E2 (CCNE2) to alter Yap nuclear localization and downstream activity of the Hippo pathway and finally regulates the movement of basal-like breast cancer cells." (PMID 35864955, 2022).
breast carcinoma (continued). "Moreover, using a dataset of breast cancer patients we show that the co-expression of HMGA1, FOXM1 and VEGFA is a negative prognostic factor of distant metastasis-free survival and relapse-free survival." (PMID 31311575, 2019). "Thus, we stratified breast cancer samples according to their relative expression levels of HMGA1 and FOXM1, obtaining a significant enrichment in VEGFA expression in patients in which the HMGA1/FOXM1 axis is activated." (PMID 31311575, 2019). "Thus, we hypothesized that HMGA1 and CCNE2 participate in breast cancer cell migration via YAP by interfering with YAP phosphorylation at Ser127 and promoting its nuclear localization." (PMID 26265440, 2015). "The first evidence linking HMGA1 to EMT came from an important study in 2001 in MCF-7 breast cancer cells, which demonstrated that forced expression of HMGA1 results in metastatic progression and histologic changes consistent with EMT in the epithelial MCF-7 breast cancer cell line." (PMID 23658826, 2013). "Therefore, PD-L1 could participate in the maintenance of CSC self-renewal by activating HMGA1-dependent signaling pathways Unfortunately, no data regarding this interaction has been reported in breast cancer." (PMID 31779212, 2019). "Interestingly, HMGA1 has been proposed to be a master regulator of tumor progression in TNBC by providing oncogenic signaling and metastatic phenotype, EMT and reprogramming TNBC cells into cancer-stem cell like state as well as poor prognosis in breast cancer patients." (PMID 28036267, 2017). "First of all, although HMGA1 is mostly nuclear in luminal breast cancer cells, it would not be unexpected that HER2-positive cells also secrete HMGA1." (PMID 31779212, 2019). "The increase of free OXPHOS mRNAs released from the YB1 complex enhanced mitochondrial activity through facilitating translation, but the stability of HMGA1 mRNA was impaired without the protection of YB1, both contributing to breast cancer cell apoptosis and reactive oxygen species production." (PMID 37035211, 2023). "Moreover, miR-181b induced by high mobility group AT-hook 1 (HMGA1) interferes with CBX7 mRNA at the translation level to inhibit its expression, resulting in a lack of CBX7 in breast cancer." (PMID 34659360, 2021). "To understand the functional involvement of HMGA1 in breast cancer malignancy we investigated whether HMGA1 alters the transcriptional programme by analysing the transcriptional profile of MDA-MB-231 cells in the presence and absence of HMGA1." (PMID 23945276, 2013).